LINC01502 (long independently transcribed non-coding RNA 1502)
Gene: Long non-coding RNA gene on chromosome 9 (135,574,935 to 135,587,112, forward strand). Ensembl gene ENSG00000237339.
Diseases named in the same sentence as LINC01502 in open-access papers:
LINC01502 is named in the same sentence as 1 disease in open-access papers, as found by Europe PMC text mining. Sharing a sentence is not in itself a finding about the gene and the disease. The quoted sentences say what the papers report.
Anxiety (1 paper, 2025). Intense feelings of nervousness, tension, or panic often arise in response to interpersonal stresses. "TAF1A at 1q41 is essential for regulating gene expression, while LINC01502, a long non-coding RNA at 9q34.3, may affect gene expression relevant to intelligence and anxiety." (PMID 40125487, 2025).